HIF1A (hypoxia inducible factor 1 subunit alpha)
Diseases named in the same sentence as HIF1A in open-access papers (continued):
Sharing a sentence is not in itself a finding about the gene and the disease.
cancer (continued). "OGT influenced HIF1a stability by controlling levels of αKG in cells as decreasing O-GlcNAcylation in cancer cells increases αKG and HIF-1α hydroxylation, leading to enhanced proteasomal degradation." (PMID 33154167, 2021). "Of note, HIF-1α-mediated upregulation of YTHDF1 under hypoxia in HCC cells provides evidence that adaptation of cancer epigenetics to hypoxic stress forces HCC malignancy, at least in part, for the translation of m6A-containing oncogene mRNAs." (PMID 33619246, 2021). "D-2 hydroxyglutarate, succinate and fumarate can affect epigenetic modifications and HIF-1α degradation and participate in the development of cancer." (PMID 33926551, 2021). "In dense-type PDAC, cancer cells closely surrounded by CAFs under hypoxic conditions mainly rely on HIF-1a-dependent aerobic glycolysis to produce energy for cellular processes." (PMID 34035226, 2021). "Proteins such as c-MYC and HIF1α are frequently stabilized and/or upregulated whereas, in the same way, lncRNAs alter signaling pathways favoring cancer progression." (PMID 33652661, 2021). "HSP90 participates in the regulation of the stability/activity of HIF-1α and its import to the nucleus, which largely defines the cancer cell adaptation to hypoxic stress." (PMID 33806538, 2021). "Collectively, FABP5 is upregulated in various cancers, which promotes cancers progression or metastasis by reprogramming fatty acid metabolism through the NF-κB signaling pathway or enhancing HIF-1α activity." (PMID 34934042, 2021). "CaLac-mediated remodeling of cancer-specific anaerobic glycolysis induced destabilization of HIF-1α and a decrease in VEGF expression, leading to the inhibition of the migration of CRC cells." (PMID 33806179, 2021). "Early research has illustrated the relation between HIF-1α and NF-κB in cancer development and progression." (PMID 34073155, 2021). "Another important role of HIF-1α and autophagy in this context is to increase the ability of the hypoxic cancer cells to activate signaling pathways that promote ATP production independently of mitochondrial oxidative phosphorylation." (PMID 33573362, 2021). "Pin1 also promotes the stability and transcriptional activity of HIF-1α to act a central regulator of glycolysis, cancer metabolism and cancer cell proliferation." (PMID 33807199, 2021). "Pin1 is known to promote angiogenesis mainly through the regulation of hypoxia-inducible factor 1α (HIF-1α)-mediated or NF-κB-mediated expression of vascular endothelial growth factor (VEGF) in cancer tissues." (PMID 33807199, 2021). "showed, that there is a link between the degradation or knockout of HIF-1α and the viability and radiosensitivity of cancer cells in vitro." (PMID 33856525, 2021). "Other studies show that HIF-1α can accelerate the efficiency of glucose metabolism and provide the energy needs for cancer cells by regulating the activity of GLUT1 and the transcription of GLUT1 mRNA." (PMID 34976805, 2021). "Similar results have been observed in clinical settings from several cohorts of patients with sporadic and hereditary breast carcinogenesis; specifically, significant overexpression of HIF-1α was reported in BRCA1-related cancers." (PMID 33513753, 2021). "Reportedly, GLUT1 expression is augmented under hypoxia through the induction of HIF1α in cancer cells." (PMID 34516556, 2021). "In this case, HIF-1α down-regulation by siRNA leads to a change in cancer metabolism from aerobic glycolysis to mitochondrial oxidative phosphorylation." (PMID 33921908, 2021). "Since phosphorylation of the ERK-targeted domain (ETD) in HIF-1α by ERK1/2 is activated in human cancers to allow HIF-1α accumulation into the nucleus, peptides that target this step have also been tested." (PMID 34071836, 2021). "The hypoxia-inducible factors-1α and -2α (HIF-1α and HIF-2α) are frequently upregulated in cancers and associated with tumor angiogenesis, cell growth and survival, and metastasis." (PMID 34887764, 2021).
cancer (continued). "The pyruvate kinase M2 (PKM2) is a glycolytic enzyme induced by HIF1α, which have roles in the development, progression, and metabolism of cancer." (PMID 34065840, 2021). "HIF-1α cannot be detected in normal cells, but cancer cells often express HIF-1α to promote their growth, angiogenesis, and high glycolysis (also known as the effect of Warburg)." (PMID 34073059, 2021). "We found that HIF‐1α expression is inversely correlated with the sensitivity of NCI‐60 cancer cells to TAM." (PMID 34841716, 2021). "Several cancer-associated mRNAs were found using the RISCTRAP assay, including ICAM1, SUMO3, HIF1A, and SEC23A." (PMID 34831007, 2021). "In the allograft mice tumor model, decursin medicates apoptosis and blocks invasion through the downregulation of HIF-1α and PD-L1 expression in hypoxia-exposed cancer cells." (PMID 34942984, 2021). "The resistance of these cancer cells, overexpressing the HIF-1α under hypoxia, to SN38-the active metabolite of irinotecan, was reduced after MSA treatment." (PMID 34205571, 2021). "Consistently, stable co-knockdown of RAC1 in HACE1 deficient cells inhibits HIF1α accumulation in these cells, suggesting targeting of RAC1 is a potential mechanistic intervention point for targeted therapy in diverse cancer types." (PMID 33603169, 2021). "BRT has been found to markedly inhibit the expression and protein synthesis of PD-L1 in various types of cancer cells, via HIF-1α/c-Myc." (PMID 34680439, 2021). "HIF-1α promotes neovascularization in solid tumors to accomplish nutrient and oxygen supply to the rapidly dividing cancer cells." (PMID 34090331, 2021). "HIF-1α is one of the best-studied oncogenes, as it transcriptionally regulates genes that facilitate cancer metastasis." (PMID 34163032, 2021). "There are no available studies examining the effect of acetate on glycolysis flux in cancer cells; however, it has been found that acetate increases the HIF-1α and HIF-2 levels in human fibrosarcoma HT1080, but after prolonged hypoxia (1% O2)." (PMID 34414111, 2021). "While the regulatory binding of HIF-1α to protein complexes inhibits the proliferative signals in some tissues, several cancer cells possess the capacity to proliferate even under hypoxic conditions." (PMID 34062959, 2021). "Lactate has also been shown to trigger calcium signaling, angiogenesis, HIF-1α stabilization, cell death, suppression of anti-cancer immune response and modulation of gene expression." (PMID 34744727, 2021). "In a variety of cancers, hypoxia arises heterogeneously in a solid tumor mass, and HIF-1α overexpression contributes to cell survival, invasiveness and metastasis as well as chemo- and radio- therapy resistance." (PMID 34611473, 2021). "Hypoxia-inducible factor-1 alpha (HIF-1α) is overexpressed in cancer, leading to a poor prognosis in patients." (PMID 34575983, 2021). "ANGPTL4, BHLHE40, and VEGF are considered as critical genes in cancer studies, which play pivotal roles in biological processes and are somehow regulated by HIF1α." (PMID 33602983, 2021). "Induced by HIF-1α, high levels of membrane-bound CAIX have been associated with cancer cell invasiveness and therapeutic resistance." (PMID 34055644, 2021). "KC7F2 suppresses HIF-1α protein synthesis in cancer cell lines U251MG, MCF7, PC3, and LNZ308 under hypoxic conditions." (PMID 34200019, 2021). "It was important to note that cancer cells are under hypoxic conditions, so even in untreated groups with CoCl2, HIF-1a protein is partially expressed in cancer cells." (PMID 34181359, 2021). "It has been established that hypoxia is in favor of cancer growth by activation of HIF-1α signaling and its downstream targets." (PMID 34943856, 2021).
cancer (continued). "Sauchinone has been reported to inhibit the growth of cancer cells by inhibiting the activity of transcription factors such as HIF-1α and STAT3." (PMID 34643237, 2021). "HIF-1α is a known oncogenic gene that accelerate glycolysis in cancer cells and is involved in the occurrence and development of CMM16,38." (PMID 33664256, 2021). "Treatment with GYY4137, a slow-releasing H2S donor, was shown to partially reverse the hypoxia-induced increase in HIF-1α protein levels and was also found to have anticancer effects in several cancer cell lines." (PMID 34200019, 2021). "E.g., within such hypoxic ‘immune deserts’, immune escape of cancers can be fostered by HIF-1α-triggered PD-L1 expression." (PMID 33718186, 2021). "Previously, it was mentioned that HIF-1α is activated in hypoxic conditions and can promote cancer progression." (PMID 33921908, 2021). "It is reported that HIF‐1α has been involved in the process of tissue fibrosis and cancer progression." (PMID 33943003, 2021). "Here, the authors define the early transcriptional response to acute hypoxia and identify HIF1A target genes as part of this acute response, providing a resource for investigating context-dependent roles of HIF1A in the biology of cancer." (PMID 33654095, 2021). "Defective melanin results in cancer melanogenesis in amelanotic cells along with an increase in HIF-1α expression." (PMID 33990669, 2021). "We found that a cytoplasmic lncRNA, namely SPRY4 intronic transcript 1 (SPRY4-IT1), mediated cell metastasis by modulating TCEB1 mRNA stability via SMD, which in turn increased HIF-1α expression and promoted the metastasis of cancer cells." (PMID 34163032, 2021). "This mode of non-canonical Notch signaling has been shown to modulate various signaling pathways such as NfKB, Pi3K, AKT, mTOR, HIF-1a, Wnt, etc., that have an important role in developmental process and cancer." (PMID 33968932, 2021). "Hypoxia-inducible factor-1α (HIF1α), which normally contributes to regulation of glycolysis in hypoxia, is also more protected from degradation in some cancer types." (PMID 34631530, 2021). "The administration of mimic miR-138 or -210 reduced the promoting effects of sevoflurane and desflurane on cancer cell proliferation and migration, in line with the HIF-1α expression changes." (PMID 33673181, 2021). "In similar studies, using cancer cells, melatonin reduced HIF-1α protein expression or destabilized this transcription factor." (PMID 33466614, 2021). "In turn, HIF-1α upregulates the HSPA2/HSP70-2 expression in cancer cells that is important for their growth and survival." (PMID 33806538, 2021). "The drugs available to interfere with HIF-1α expression or activity have been developed in the field of cancer and with the final purpose to induce targeted cell death." (PMID 34281273, 2021). "HIF-1A is a transcription factor expressed in the cytoplasm or/and nucleus of many cancers, but rarely detected in the normal control tissues." (PMID 33403040, 2021). "The important roles of lncRNAs in the regulation of HIF1α in cancer have been demonstrated previously." (PMID 33652661, 2021). "As there is a close relationship between HIF-1α and cancer metabolism, targeting this molecular pathway is of importance in CP sensitivity." (PMID 33921908, 2021). "In several cancer cell lines, mTORC1 signaling supports the HIF-1α response by inhibiting HIF-1α degradation and/or promoting its production." (PMID 33782423, 2021). "In particular, HIF-1α has been found to promote the stemness of cancer cells through the regulation of several pathways, including PI3K/Akt/mTOR, Wnt/β‐catenin, and Notch signaling." (PMID 33461544, 2021). "Epigenetic-mediated positive regulation of HIF1-α-induced glycolysis through lncRNA has also been reported, but in cancers other than CRC." (PMID 34571724, 2021). "All of these would limit the clinical application of targeting the HIF1A protein for predicting the prognosis of cancer patients." (PMID 34439934, 2021).
cancer (continued). "A substantial body of evidence has established that activation of the HIF-1α pathway is responsible for shaping the phenotype, metabolism, and activity of cancer cells." (PMID 34479492, 2021). "Here, HIF-1α serves as a marker for hypoxia correlated with malignant properties and increased patient mortality in many different types of cancer." (PMID 34671319, 2021). "Hypoxia‐inducible factor 1‐alpha (HIF‐1α) can induce cancer cell resistance to tamoxifen and fulvestrant treatment, and its over‐expression in ERα+ patients is associated with poor survival to endocrine therapy." (PMID 34651424, 2021). "In summary, combined targeting of CDK(s) (CDK1 or CDK4/6) and HSP90 remarkably inhibits the expression level of HIF1α and shows promising anti-cancer efficacy with therapeutic potential." (PMID 34686682, 2021). "A human cancer cell study has shown that HIF1A and EPAS1 transcriptional response to hypoxia varies among human cells." (PMID 34724959, 2021). "Due to its important role in cancer development and progression, several studies in this regard have been directed to HIF1α." (PMID 34209205, 2021). "Hypoxia-inducible factor-1 alpha (HIF-1α), the most important regulator of hypoxia-related mechanisms, is often overexpressed in human cancers and associated with the poor prognosis." (PMID 34869045, 2021). "Overexpression of HIF-1α seen in several cancers is responsible for drug resistance and higher mortality." (PMID 34829751, 2021). "Metabolic reprogramming similar to that observed in cancer, driven by HIF1A, likely allows D4 liver to continue efficient energy production under hypoxia, while increasing angiogenesis to eventually escape these conditions as the chick matures." (PMID 34030631, 2021). "Emodin and rhein can decrease HIF-1α expression and attenuate cancer cachexia in athymic mice carrying cancer cells." (PMID 34257692, 2021). "Culture in hypoxia can expand the CD133+ glioma cancer stem cells through activation of hypoxia inducible factor 1α (HIF1α)." (PMID 33453053, 2021). "In this study, we observed that HIF-1α and Beclin1 were expressed both in cancer tissue and adjacent normal tissues." (PMID 34465721, 2021). "The hypoxic cancer microenvironment induces autophagy through initiation of the stress response signalling mechanism hypoxia-induce factor-1 alpha (HIF-1α), which alleviates the energy deprivation, thus enhancing the cancer progression and survival." (PMID 33802014, 2021). "Hypoxia would further induce Hypoxia-inducible factor-1 alpha (HIF-1α) expression, facilitating the cancer cell adaptation in the oxygen-deficient TME." (PMID 33927716, 2021). "HSP70 is directly involved in the cancer cell response to hypoxia, as its chaperone activity is required for the folding, stabilization and nuclear translocation of HIF-1α." (PMID 33806538, 2021). "We have determined the relationship of HIF‐1α with cancer aggressiveness and its potential role as a therapeutic target." (PMID 33773069, 2021). "Owing to the overexpression of COX-2 and HIF-1α in human cancers, their inhibition is considered to be the effective therapeutic strategy to target the angiogenesis and cell proliferation." (PMID 34715860, 2021). "The dysregulation, overexpression or genetic alterations of hypoxia-inducible factor 1-alpha, also known as HIF-1α, have been profoundly associated with cancer biology, which qualifies HIF-1α as a therapeutically valuable target in cancer therapy." (PMID 34575464, 2021). "Hypoxia inducible factor 1-alpha (HIF1α) is a main regulator of transcriptional response to hypoxia in cancer cells." (PMID 34221996, 2021). "In the NPC model, exosomal cell-to-cell transmission of transcriptionally active HIF1α promotes cancer progression and invasive potential, through induction of EMT." (PMID 34209290, 2021). "Hypoxia inducible factor 1- alpha (HIF-1α) up-regulation is involved in cancer cell proliferation, metastasis, resistance to therapy and worse prognosis." (PMID 33544704, 2021).
cancer (continued). "Based on our new mechanism, the inhibition of Hsp90 emulates this by hitting K-Ras (in particular in HIF-1α–high, Gal3-high cancers) in addition to Raf and ERK." (PMID 33672199, 2021). "Apart from leading to lipid synthesis, hypoxia also suppresses lipolysis/β-oxidation via HIF-1α-induced downregulation of medium- and long-chain acyl-CoA dehydrogenase, and accumulation of lipid droplets promotes cancer progression." (PMID 33436044, 2021). "Under hypoxic conditions, HIF-1α is stabilized, binds DNA, and regulates the transcription of glycolytic target genes in cancer cells." (PMID 33718197, 2021). "HIF-1α is one of the central molecules that mediate the development of cancer and is a key regulator of VEGF." (PMID 33865381, 2021). "The impressive number of inhibitors that have been studied reflects the huge interest in targeting HIF-1α in cancer therapy and the significance of identifying and characterizing its impact in relative cellular pathways." (PMID 34359734, 2021). "In our experimental setup we found an increased HIF-1α genes and protein expression at 72 h after sevoflurane exposure in cancer cell lines." (PMID 34199634, 2021). "The metastatic potential of cancer can be enhanced by HIF-1α target genes, such as angiopoietin-like 4 (ANGPTL4), lysyl oxidase (LOX), and lysyl oxidase-like 4 (LOXL4)." (PMID 34575983, 2021). "In line with this, multiple studies have reported that HIF-1α-positive cancer cells are located in the invasive front of cancer tissue and are closely related to metastasis." (PMID 34916607, 2021). "The present study reveals that the expression of MOF in cancer tissues is inversely related to the expression of HIF-1α." (PMID 34540836, 2021). "Anaerobic glycolysis is a common metabolic pathway adopted by hypoxic cancer cells and is regulated by hypoxia-inducible factor (HIF)-1α." (PMID 33806179, 2021). "Among them, the Notch signaling pathway activated by HIF-1α under hypoxic conditions, is essential for maintaining the stemness of cancer stem cells." (PMID 33397409, 2021). "Cancer cells in hypoxic condition activate related pathways to adapt the hypoxia, and the elevated HIF-1α level was the indication of HIF-1α signal pathway activation." (PMID 33441708, 2021). "VEGF, together with HIF1α, are also considered as important factors involved in cancer progression and dissemination." (PMID 33540843, 2021). "As yet, no studies separately investigated the effect of cytoplasmic and nuclear HIF-1A expression on cancer patient progression." (PMID 33403040, 2021). "Hypoxia-inducible factor-1α (HIF-1α) activates the transcription of genes involved in cell proliferation and metastasis in cancers." (PMID 34988077, 2021). "The expression of HIF-1α in the hypoxic microenvironment promotes cancer glycolysis and evasion of immunosurveillance to promote the function of CD8+ T cells." (PMID 34869309, 2021). "The reduction in HIF1α mRNA expression in hypoxia indicates that this molecule may be important for cellular adaptation to hypoxia, and this hypothesis is supported by the observation that high levels of HIF1α mRNA have been observed in some cancers and are often associated with poor prognosis." (PMID 34162983, 2021). "Meanwhile, PKM2 stimulates HIF-1α transactivation, it complements P300 in response to hypoxic conditions and occurs in activated immune cells and cancer cells." (PMID 33995634, 2021). "HIF1α/VEGF signaling has been heavily implicated in the angiogenesis during many conditions, such as joint osteoarthritis, ischemia, and cancers." (PMID 34963484, 2021).